NBPF1 (NBPF member 1)
Synonyms: KIAA1693; FLJ20719; AB13; AB14; AB23; AD2; NBG; NBPF
Tractability: PROTAC: ubiquitination databases record sites on it.
Gene: Protein-coding gene on chromosome 1 (16,562,319 to 16,613,562, reverse strand). Ensembl gene ENSG00000219481.
Subcellular location: Cytoplasm
Subcellular location (Human Protein Atlas): Cytosol; Primary cilium; Cytokinetic bridge; End piece; Golgi apparatus; Microtubules; Mid piece; Principal piece; Vesicles
Gene Ontology:
Molecular function: protein binding
Cellular component: cytoplasm
Genetic constraint (gnomAD): Loss-of-function variants: 6 observed, 31.92 expected, observed/expected ratio (o/e) 0.19, 90% interval 0.1 to 0.37. The synonymous counts are far from expectation, so gnomAD's model fits this gene poorly and the ratio says little. Missense variants: 197 observed, 347.59 expected, observed/expected ratio (o/e) 0.57, 90% interval 0.5 to 0.64. Synonymous variants: 43 observed, 108.72 expected, observed/expected ratio (o/e) 0.4, 90% interval 0.31 to 0.51.
Homologues: Paralogues in human: NBPF12 (94% identical), NBPF14 (72% identical), NBPF9 (72% identical), NBPF10 (72% identical), NBPF26 (72% identical), NBPF8 (72% identical), NBPF11 (62% identical), NBPF20 (50% identical), NBPF19 (50% identical), NBPF15 (50% identical), NBPF3 (35% identical), NBPF4 (22% identical), and 1 more.